CEP85 (centrosomal protein 85)
Description:
Acts as a regulator of centriole duplication through a direct interaction with STIL, a key factor involved in the early steps of centriole formation. The CEP85-STIL protein complex acts as a modulator of PLK4-driven cytoskeletal rearrangements and directional cell motility. Acts as a negative regulator of NEK2 to maintain the centrosome integrity in interphase. Suppresses centrosome disjunction by inhibiting NEK2 kinase activity.
Synonyms: CCDC21; DKFZP434L0117
Tractability: PROTAC: ubiquitination databases record sites on it.
Gene: Protein-coding gene on chromosome 1 (26,233,669 to 26,278,814, forward strand). Ensembl gene ENSG00000130695.
Subcellular location: Cytoplasm, cytoskeleton, microtubule organizing center, centrosome; Cytoplasm, cytoskeleton, spindle pole; Nucleus, nucleolus; Cytoplasm, cytoskeleton, microtubule organizing center, centrosome, centriole; Cytoplasm, cell cortex
Subcellular location (Human Protein Atlas): Golgi apparatus; Nucleoli; Centrosome; Cytosol; Vesicles
Gene Ontology:
Molecular function: identical protein binding; protein binding
Biological process: cell migration; centriole assembly; centriole replication; negative regulation of protein kinase activity; regulation of mitotic centrosome separation
Cellular component: cell cortex; centriole; centrosome; cytosol; nucleolus; pericentriolar material; spindle pole
Genetic constraint (gnomAD): Loss-of-function variants: 50 observed, 80.74 expected, observed/expected ratio (o/e) 0.62, 90% interval 0.49 to 0.78. The upper end of that interval is the gene's LOEUF score, 0.78, which puts it in group 3 of 6, group 1 being the genes least tolerant of losing a copy. Missense variants: 809 observed, 886.6 expected, observed/expected ratio (o/e) 0.91, 90% interval 0.86 to 0.97. Synonymous variants: 290 observed, 323.68 expected, observed/expected ratio (o/e) 0.9, 90% interval 0.81 to 0.99.
Homologues: Orthologues: chimpanzee CEP85 (99% identical), macaque CEP85 (98% identical), dog CEP85 (91% identical), pig CEP85 (91% identical), guinea pig CEP85 (88% identical), mouse Cep85 (86% identical), rat Cep85 (85% identical), rabbit CEP85 (83% identical), zebrafish cep85 (44% identical), tropical clawed frog cep85 (42% identical). Paralogues in human: CEP85L (34% identical).
Diseases named in the same sentence as CEP85 in open-access papers:
CEP85 is named in the same sentence as 3 diseases in open-access papers, as found by Europe PMC text mining. Sharing a sentence is not in itself a finding about the gene and the disease.
CEP85 shares sentences with these, for which no sentence is quoted: cancer (2 papers); glioblastoma (1); tumor (1).